HDAC1 (histone deacetylase 1)
Diseases named in the same sentence as HDAC1 in open-access papers (continued):
Sharing a sentence is not in itself a finding about the gene and the disease.
hepatoblastoma (5 papers, 2023 to 2024). Hepatoblastoma (HB) is a malignant hepatic tumor and is the most common pediatric liver cancer. "HDAC1-mediated inhibition of hepatocyte markers is a critical stage in the formation of hepatoblastoma, laying the groundwork for the development of treatments for aggressive hepatoblastoma by inhibiting HDAC1 activity." (PMID 37923899, 2023). "Evidence for synergy with drugs inhibiting HDAC1 along with cisplatin have been reported in vivo in hepatoblastoma models as well as through connectivity mapping." (PMID 37568737, 2023). "In hepatoblastoma (HBL), HDAC1 delivered to the promoter of the p21 gene by another transcription factor, sp5, and activated p21 expression, thereby promoting the proliferation and metastasis of HBL cells." (PMID 37760477, 2023).
liposarcoma (5 papers, 2017 to 2025). A usually painless malignant tumor that arises from adipose tissue. "HDAC1 (Histone deacetylase 1) somatic mutations are observed in 8.3% of patients with dedifferentiated liposarcoma." (PMID 33498189, 2021). "For example, in a panel of liposarcoma cell lines, the expression of HDAC1 correlated with sensitivity to quisinostat." (PMID 41319167, 2025). "Dedifferentiated liposarcomas (DLPS) harbor histone deacetylase 1 (HDAC1) mutations in 8.3% of cases, and liposarcoma methylomes show alteration in differentiation genes, including CCAAT/Enhancer Binding Protein Alpha (CEBPA) methylation in 24% of cases." (PMID 28654693, 2017).
lymph node metastasis (5 papers, 2012 to 2023). "Pearson chi-square test indicated a low expression of HDAC1 in carcinoma samples of bitches with lymph node metastasis (p = 0.035)." (PMID 38028583, 2023). "Here, we reported that HDAC1 expression was elevated in cancerous tissue and correlated with lymph node metastasis and poorer overall survival in patients with GBC." (PMID 27092878, 2016). "Increased expression of HDAC1 was correlated with histological grade (P < 0.001), age (P = 0.004), clinical stage (P = 0.007) and lymph node metastasis (P = 0.001)." (PMID 22455563, 2012). "In addition, we performed meta-analyses to determine the relationship between HDAC1 expression and the clinical features of gastrointestinal malignancies, and correlations between HDAC1 expression and tumor stage, grade, lymph node metastasis and distant metastasis were observed." (PMID 28424407, 2017).
osteoporosis (5 papers, 2016 to 2024). A condition of reduced bone mass, with decreased cortical thickness and a decrease in the number and size of the trabeculae of cancellous bone (but normal chemical composition), resulting in increased fracture incidence. "More importantly, we found an inhibitory role of Hdac1 in regulating bone formation in response to hindlimb unloading in mice, and pretreatment with an HDAC1 inhibitor partly rescued the osteoporosis caused by mechanical unloading." (PMID 27171263, 2016). "For the TFBSs, we identified 2 TFBSs (EZH2 and RAD21) for enrichment, and 2 TFBSs (ELK4 and HDAC1) for depletion in the promoters of osteoporosis-associated genes, respectively." (PMID 27465306, 2016). "In this study, we found that HDAC1 was negatively correlated with osteogenic differentiation and bone formation in the BMSCs of patients with osteoporosis, whereas jagged 1 (JAG1)-mediated NOTCH signaling was upregulated." (PMID 27171263, 2016). "However, we also observed that CMS modulated JAG1 expression by modifying the histone acetylation status of JAG1, as the inhibition of HDAC1 only partially rescued the mechanical unloading-induced osteoporosis in mice." (PMID 27171263, 2016). "HDAC1 was found to inhibit bone formation and Notch signalling via deacetylating JAG1 and inhibiting HDAC1 attenuated hind limb unloading induced osteoporosis [45••]." (PMID 32794139, 2020).
peripheral T cell lymphoma (5 papers, 2020 to 2025). "Chidamid, an oral HDAC inhibitor of the benzamide class with specificity for HDAC1, HDAC2, HDAC3, and HDAC10 subtypes, has been approved for the treatment of relapsed or refractory peripheral T cell lymphoma." (PMID 41049003, 2025). "Tucidinostat, a selective HDAC inhibitor having specificity for HDAC1, HDAC2, HDAC3, and HDAC10 subtypes, has been approved for the treatment of relapsed or refractory peripheral T cell lymphoma and is under clinical development globally for various other neoplastic and non-neoplastic diseases." (PMID 36352411, 2022).
psoriasis (5 papers, 2015 to 2022). An autoimmune condition characterized by red, well-delineated plaques with silvery scales that are usually on the extensor surfaces and scalp. "HDAC1 was overexpressed in psoriasis patients while SIRT1 was decreased in the basal layer of psoriasis patients compared to healthy controls." (PMID 35280995, 2022). "Among the patients with psoriasis, expression of HDAC1, p63, and PCNA was significantly higher in plaque psoriasis than in guttate psoriasis." (PMID 32825671, 2020). "Lesional skin biopsies from psoriasis patients show increased expression of HDAC1 when compared to controls." (PMID 31333659, 2019). "In patients with psoriasis, elevated mRNA levels of HDAC1 compared to healthy controls were noted." (PMID 35163689, 2022). "The fact that HDAC1 expression levels were higher in plaque psoriasis suggests that HDAC1 could have a more important role in chronic and severe psoriasis." (PMID 32825671, 2020). "HDAC1 was expressed throughout the epidermis in both plaque and guttate psoriasis." (PMID 32825671, 2020). "The role of SIRT1 in psoriasis is opposite to that of HDAC1." (PMID 32825671, 2020). "Increased expression of HDAC1 and IL-17 in psoriasis suggests that HDAC1 may be a suitable target of future therapeutic interventions." (PMID 31333659, 2019). "Perhaps in the psoriasis Treg cells treated with trichostatin-A occurred that when HDAC-1 was inhibited, the expression of VHL augmented, HIF-1α was proteolyzed, and the expression of IL-17 decreased, giving as result that Treg cells could not switch to Th17." (PMID 26136626, 2015). "In addition, HDAC1 expression levels were higher in plaque psoriasis than in guttate psoriasis." (PMID 32825671, 2020). "HDAC1 mRNA has been reported to be overexpressed in lesional skin and peripheral blood mononuclear cells (PBMC) of patients with psoriasis." (PMID 32825671, 2020). "The expression of HDAC1, SIRT1, p63, and PCNA was compared between patients with psoriasis and healthy controls using immunohistochemistry." (PMID 32825671, 2020). "The expression of HDAC1, p63, and PCNA was significantly higher in the plaque psoriasis group than in the guttate psoriasis group (p < 0.01, p < 0.01, and p < 0.05, respectively)." (PMID 32825671, 2020). "Abnormal histone modification by histone deacetylases (HDACs), including HDAC1 and sirtuin 1 (SIRT1), has been reported to play an important role in the pathogenesis of psoriasis by altering cell proliferation, differentiation, and inflammation." (PMID 32825671, 2020). "Furthermore, there were significant differences in the expression levels of HDAC1 as well as p63 and PCNA between plaque and guttate psoriasis." (PMID 32825671, 2020). "Increased expression of HDAC1, together with p63 and PCNA biomarkers, could contribute to the formation of clinical phenotypes of psoriasis." (PMID 32825671, 2020). "The expression of HDAC1 and keratinocyte proliferative markers, such as p63 and PCNA significantly increased, whereas that of SIRT1 decreased in the basal layer (p < 0.05) of the patients with psoriasis compared to those in healthy controls." (PMID 32825671, 2020). "HIF-1α and its regulators (HDAC-1, HDAC-7, VHL-E3, PHD2, LL-37, HIF-1β, mTOR, miR-210, RORγt, STAT3, and IL-13Ralpha, as well as glycolysis enzymes) could be important pharmacological targets to restore the lack of regulation in the angiogenesis and in immunological processes involved in psoriasis." (PMID 26136626, 2015).
renal cell carcinoma (5 papers, 2008 to 2026). "A recent research study showed that HDAC-1, -2 and -3 were highly expressed in renal cell carcinoma and overexpression of HDAC1 was reported to associate with a poor prognosis." (PMID 26698299, 2015). "In renal cell carcinomas moderate to strong nuclear HDAC1, HDAC2 and HDAC3 immunoreactivity was detected in 55.7%, 56.6% and 13.2% of cases, respectively." (PMID 19099586, 2008). "In renal cell carcinoma (RCC), UHRF1 recruits histone deacetylase 1 (HDAC1) into the TXNIP promoter, reducing TXNIP expression and promoting the progression of RCC." (PMID 35450411, 2022).
sarcoma (5 papers, 2016 to 2024). A usually aggressive malignant neoplasm of the soft tissue or bone. "We analyzed the TCGA public database of 263 STS samples (cBioPortal.org) to identify the potential role of HDACs in sarcoma and observed an association between higher expression of class I HDACs, including HDAC1, HDAC2 and HDAC3 with shorter overall survival (p<0.001)." (PMID 33637599, 2021). "The previous results showed that the expression of class I HDACs, including HDAC1, HDAC2, and HDAC3, is associated with a poor prognosis of patients with sarcoma." (PMID 33637599, 2021). "Histone deacetylase (HDAC) class I genes HDAC1, 2, 3, and 8 are widely expressed in different pediatric sarcomas and other pediatric and adult tumor entities." (PMID 34654445, 2021). "We found that the mRNA expression of HDAC class I genes HDAC1, HDAC2 and HDAC3 was associated with prognosis in sarcoma." (PMID 33637599, 2021). "Fused in sarcoma has also been shown to be involved in DNA damage and DNA repair by interacting directly with HDAC1." (PMID 28082870, 2016). "Since class I HDACs affect cell proliferation, we also detected the expression of HDAC1, HDAC2, and HDAC3 after treatment with chidamide and founded inhibited expression of HDAC1, HDAC2, and HDAC3 in the three sarcoma cell lines." (PMID 33637599, 2021).
anaplastic large cell lymphoma (4 papers, 2020 to 2025). Anaplastic large cell lymphoma (ALCL) is a rare and aggressive peripheral T-cell non-Hodgkin lymphoma, belonging to the group of CD30-positive lymphoproliferative disorders, which affects lymph nodes and extranodal sites. "Conversely, HDAC1 acts as a tumor suppressor in ALK-positive anaplastic large cell lymphoma." (PMID 41444923, 2025).
anemia (4 papers, 2018 to 2024). A reduction in the number of red blood cells, the amount of hemoglobin, and/or the volume of packed red blood cells. "Knockout of histone deacetylases HDAC1 or HDAC2 affects hematopoiesis, while simultaneous knockout of HDAC1 and HDAC2 results in severe HSC defects, leading to anemia and reduced blood cell counts, indicating functional redundancy between HDAC1 and HDAC2 in hematopoiesis." (PMID 39445003, 2024).
Arrhythmia (4 papers, 2013 to 2025). Any cardiac rhythm other than the normal sinus rhythm. "The knockout of both HDAC1 and HDAC2 in the heart can lead to severe arrhythmia and dilated cardiomyopathy, whereas the deletion of one gene does not affect heart development, indicating functional redundancy between HDAC1 and HDAC2." (PMID 40102393, 2025). "Arrhythmia and the cardiac chamber enlargement in bigheart may be a result of altered calcium handling, possibly via the Camk2d-Hdac1 pathway." (PMID 38533084, 2024). "Knockout of both HDAC-1 and -2 seems to result in incapacity of REST to repress these fetal genes, resulting in, among other things, arrhythmia." (PMID 24198825, 2013). "While myocardium-specific deletion of either HDAC-1 or HDAC-2 results in no apparent cardiac phenotype, specific deletion of both in the murine myocardium, results in death within 2 weeks after birth, due to cardiac arrhythmias and dilated cardiomyopathy." (PMID 24198825, 2013).
astrocytoma (4 papers, 2017 to 2026). "NUSAP1 also upregulated the expression of the downstream targets of HH pathway including PTCH1, HIP1, CCND1, CCNE1 and HDAC1 in astrocytoma." (PMID 28899410, 2017). "Analysis of the SHAP values for the remaining genes revealed that increased expression of ZDHHC18, HDAC1, and TUBB6 enhances the probability of predicting astrocytoma, while elevated expression of TERT, TRIM67, NOG, KCNIP2, and KCNJ11 increases the probability of predicting oligodendroglioma." (PMID 40867242, 2025).
autoimmune disease (4 papers, 2015 to 2026). A disorder resulting from loss of function or tissue destruction of an organ or multiple organs, arising from humoral or cellular immune responses of the individual to their own tissue constituents. "Our work suggests that p300 and HDAC1 may be novel targets for the treatment of RORγt-mediated autoimmune diseases." (PMID 26549310, 2015). "Therefore, the HDAC1 inhibitor is still risky as a potential treatment for correcting epigenome alterations in SLE patients due to its concomitant effect of augmenting the IFN signature in autoimmune diseases." (PMID 36719379, 2023).
bone cancer (4 papers, 2017 to 2025). A primary or metastatic malignant neoplasm affecting the bone or articular cartilage. "Bone cancer caused significantly increased expression of HDAC1 in spinal microglia and neurons, with HDAC2 markedly increased in spinal astrocytes, which were accompanied by the upregulation of MAPK pathways and the activation of microglia and astrocytes in the SDH." (PMID 29096654, 2017). "In a rat model of bone cancer pain, HDAC1 was upregulated in neurons and astrocytes in the dorsal horn, while HDAC2 was upregulated in astrocytes." (PMID 38138971, 2023). "In a rat model of bone cancer pain, HDAC1 was upregulated mainly in neurons and microglia of the spinal dorsal horn, while HDAC2 was upregulated in spinal astrocytes; both enzymes were upregulated in satellite glial cells of the DRG." (PMID 38138971, 2023). "Previous studies reported the same trend of variation in HDAC1 and HDAC2 in bone cancer pain models." (PMID 31024248, 2019). "Third, bone cancer induced significant upregulation of MAPK signaling pathways and expression increase of HDAC1 in the microglia and neurons in the SDH as well as remarkable increase of HDAC2 in astrocytes, which were effectively inhibited by T10 treatment." (PMID 29096654, 2017).
brain tumor (4 papers, 2018 to 2022). "A similar epigenetic mechanism in which Hdac1 and Rbbp4 associate with oligoneural precursor transcription factors might drive zebrafish rb1 brain tumor oncogenesis." (PMID 29914980, 2018). "The aim of this work is the development of a novel 18F-labelled HDAC1/2-specific inhibitor with a benzamide-based zinc-binding group to visualize these enzymes in brain tumours by positron emission tomography (PET)." (PMID 35337122, 2022). "The aim of this work is the development of a novel 18F-labelled HDAC1/2-specific inhibitor with a benzamide-based ZBG for targeting these enzymes in brain tumours." (PMID 35337122, 2022). "To this end, we specifically investigated the functional importance of HDAC1 in GSCs, an HDAC isoform whose expression increases with brain tumor grade and is correlated with decreased survival." (PMID 34494550, 2021). "Examining the contribution of HDAC1 and RBBP4 to maintaining the progenitor-like state of RB1 brain tumors would shed light on the mechanism of chromatin remodeling in epigenetic control of tumor suppression." (PMID 29914980, 2018).
breast invasive ductal carcinoma (4 papers, 2012 to 2022). "McNemar's consistency test showed that the consistency of HDAC1 and KLF5 expression in patients with invasive ductal carcinoma was statistically significant (kappa=0.287, P<0.001)." (PMID 35342356, 2022). "Immunohistochemical staining of HDAC1, HDAC2, and HDAC3 in 161 samples from breast invasive ductal carcinoma patients, including 63 patients with brain metastasis, was performed using the standard streptavidin‐peroxidase method." (PMID 32686908, 2020). "However, the expression levels of histone deacetylase 1 in breast invasive ductal carcinoma do not appear to have been studied." (PMID 22455563, 2012).
chronic myeloid leukemia (4 papers, 2008 to 2024). "KEGG pathway analysis revealed that four hub genes- ABL1, HDAC1, HDAC2 and MDM2 - were primarily associated with chronic myeloid leukemia (KEGG:05220 and P = 3.27E-08) and notch signaling pathway (KEGG:04330 and P = 2.38E-04)." (PMID 38832038, 2024). "Agreeing with the known functions, pathway annotations such as “epigenetic regulation of gene expression” (Reactome pathway, P = 2.87e-13), and “chronic myeloid leukemia” (KEGG pathway, P = 1.61e-08) are enriched among HDAC1 network neighbors." (PMID 27333808, 2016).
congestive heart failure (4 papers, 2024 to 2025). Failure of the heart to pump a sufficient amount of blood to meet the needs of the body tissues, resulting in tissue congestion and edema. "The congestive heart failure-associated targets were Dnmt1, Hdac1, Hdac4, Ezh2, Sirt3, Kdm2a, Prkca and Prkcb (9.8% of total targets)." (PMID 40076868, 2025). "The HDAC1 and 2 levels are overexpressed in congestive heart failure, suggesting that their inhibition by mocetinostat could be beneficial in this pathology." (PMID 39768722, 2024). "The expression of class I HDAC isoforms, such as HDAC1 and 2, is upregulated in congestive heart failure (CHF) and also in CD90+cardiac fibroblasts." (PMID 40660005, 2025). "In a murine model of congestive heart failure (CHF), HDAC1 and HDAC2 also contributed to MF by participating in the IL‐6/STAT3 signalling pathway." (PMID 40497340, 2025).
diffuse large B-cell lymphoma (4 papers, 2008 to 2022). "HDAC1 has also been reported to be highly expressed in some lymphomas, including diffuse large B-cell lymphoma (DLBCL), peripheral T-cell lymphoma (PTCL), and Hodgkin’s lymphoma (HL)." (PMID 36497084, 2022). "In a previous study, following treatment with the HDAC-1-specific inhibitor MS-275, the expression of CIITA and MHC class II in diffuse large B-cell lymphoma (DLBCL) cells was upregulated." (PMID 25815463, 2015).
experimental autoimmune encephalomyelitis (4 papers, 2020 to 2025). An autoimmune demyelinating disease of the central nervous system that is produced experimentally in animals by the injection of homogenized brain or spinal cord in Freund's adjuvant. "RNF157 enhances Th1 cell differentiation and reduces Th17 cell differentiation by modulating HDAC1 ubiquitination, thus curbing experimental autoimmune encephalomyelitis." (PMID 40436857, 2025). "Mice with a conditional deletion of HDAC1 have shown to be resistant to experimental autoimmune encephalomyelitis (EAE), a common animal model of MS." (PMID 32241259, 2020).